NOD2 (nucleotide binding oligomerization domain containing 2)
Diseases named in the same sentence as NOD2 in open-access papers (continued):
Sharing a sentence is not in itself a finding about the gene and the disease.
Blau syndrome (continued). "In contrast, gain-of-function mutations of NOD2 have been associated with other inflammatory disease, such as Blau syndrome and early-onset-sarcoidosis (EOS)." (PMID 31379806, 2019). "The autoinflammatory disease Blau syndrome (BS)/early-onset sarcoidosis (EOS) is caused by a point mutation of Nod2." (PMID 29259708, 2017). "Functional activation by genetic mutations of Nod2 is associated with autoinflammatory diseases, Blau syndrome (BS), and early-onset sarcoidosis (EOS), which are characteristics of systemic granulomatous diseases." (PMID 29259708, 2017). "It was also discovered that an autoinflammatory disease, Blau syndrome (BS)/early-onset sarcoidosis (EOS), was caused by a point mutation of Nod2, encoding a constitutively active form, resulting in NF-κB activation." (PMID 27403452, 2016). "SNPs in the innate immune receptor nucleotide oligomerisation domain 2 (NOD2) can cause the inflammatory disorders Blau Syndrome (BS) and early onset sarcoidosis (EOS) through receptor hyperactivation." (PMID 25093298, 2014). "This study aimed to assess the clinical characteristics, long-term progression, and functional implications of NOD2 variants in a group of twelve children diagnosed with SURF, along with two Blau syndrome cases and two healthy controls." (PMID 41357180, 2025). "One immune-related example is NOD2, a gene involved in Blau syndrome, which is a rare autosomal dominant autoinflammatory syndrome classified as an autoinflammatory phenotype." (PMID 40406108, 2025). "As a NOD2-dependent autoinflammatory granulomatosis, Blau syndrome is a good model to investigate the mechanism of granuloma formation." (PMID 37415984, 2023). "In the context of Blau syndrome, NOD2 mutations are primarily confined to the NBD region, resulting in an overactivation of the NOD2 phenotype." (PMID 37869013, 2023). "The JAK inhibitor tofacitinib is a potential therapeutic agent for Blau syndrome because it suppresses the autoinflammation seen in Blau syndrome by inhibiting the expression of NOD2." (PMID 37415984, 2023). "Notably, Blau syndrome and EOS are a result of Nucleotide-binding oligomerization domain-containing protein 2 (NOD2), previously known as CARD15 gene mutation." (PMID 37721575, 2023). "In this study, we focused on ex vivo studies using a luciferase assay system overexpressing the NOD2 mutant and iPS-ML cells differentiated from iPS cells derived from a Blau syndrome patient." (PMID 37415984, 2023). "To evaluate the anti-inflammatory effect of tofacitinib in Blau syndrome, we focused our attention on the upstream pathway of NOD2." (PMID 37415984, 2023). "Along with the induction of NOD2 expression by IFNγ treatment, TNFA expression was induced not only in cells with the p.R334W mutation associated with Blau syndrome, but also in WT cells." (PMID 37415984, 2023). "The effect of tofacitinib on the upstream pathway for the induction of NOD2 expression and proinflammatory cytokine production was assessed using monocytic cell lines differentiated from Blau syndrome patient-derived induced pluripotent stem cells." (PMID 37415984, 2023). "Precisely how NOD2 activation induces granuloma formation in Blau syndrome remains to be elucidated." (PMID 37415984, 2023). "The IFNγ signal has been reported to be increased in localized skin lesions of idiopathic sarcoidosis and Blau syndrome and IFNγ upregulates the expression of NOD2, acting as a priming signal, as previously reported." (PMID 35711422, 2022). "Although pathological studies reveal that granulomas in Blau syndrome patients are accompanied by a prominent expression of IFN-γ, the details regarding the molecular mechanism(s) by which NOD2 mutations drive the pathogenesis of Blau syndrome are unclear." (PMID 35603217, 2022). "Blau syndrome (MIM #186580) is a rare, systemic granulomatous disease caused by mutations in the nucleotide-binding oligomerization domain 2 (NOD2) gene and is inherited in an autosomal dominant manner." (PMID 35711422, 2022).
Blau syndrome (continued). "This was established through iPS cells from patients with Blau syndrome that were differentiated into macrophages and confirmed that IFNγ treatment enhanced the expression of NOD2." (PMID 35711422, 2022). "Blau Syndrome (BS) is an autosomal dominant disorder caused by mutations in Card15, the gene encoding the NOD-like Receptor (NLR) protein, NOD2, and is characterized by granulomatous inflammation of the skin, joints and eyes, but rarely, if ever, the GI tract." (PMID 36189261, 2022). "Extremely low (nucleotide-binding oligomerization domain containing 2 (NOD2) mosaicism was verified in a patient with the mild phenotype of Blau syndrome." (PMID 34362117, 2021). "As suggested by the results of in vitro experimental findings, constitutive NF-κB activation in NOD2-expressing APC is considered responsible for granuloma formation in Blau syndrome." (PMID 33923123, 2021). "Recently, nucleotide-binding oligomerization domain 2 NOD2 mutations were involved in the pathogenesis of sarcoidosis, as well as in Blau syndrome (BS) and early onset sarcoidosis (EOS)." (PMID 32751786, 2020). "It is understandable that Blau syndrome mimics intracellular bacterial infection because NOD2 acts as an intracellular sensor for muramyl dipeptide, the common component of bacterial cell wall peptidoglycan." (PMID 32256502, 2020). "Blau syndrome and early-onset sarcoidosis are the two forms of pediatric granulomatous arthritis caused by mutations in the NOD2/CARD15 gene encoding NOD2." (PMID 31736939, 2019). "Patients with Blau syndrome exhibit granulomatous dermatitis, arthritis, and uveitis Although, again the autoactivation of NOD2 driving disease has also been questioned." (PMID 31131275, 2019). "The first one is a monogenic autoinflammatory disease caused by mutations in the CARD15/NOD2 gene, that includes Blau syndrome and early-onset sarcoidosis, which are the familial and the sporadic forms of the same disease spectrum." (PMID 29954416, 2018). "Blau syndrome (BS, OMIM # 186580) is an autosomal dominant granulomatous disease caused by a mutation in CARD15/NOD2 gene." (PMID 28588486, 2017). "NOD2 mutations confer highest risks for CD, but also for Graft-versus-host disease (GVHD) and Blau syndrome." (PMID 28253332, 2017). "This type of inflammation rarely affects the lungs or intrathoracic lymph nodes in Blau syndrome, and only one pediatric case with the R334Q CARD15/NOD2 mutation has been associated with interstitial pneumonia." (PMID 27983684, 2016). "Moreover, seven NOD2 mutations that may be associated Blau syndrome have been identified." (PMID 25692065, 2015). "Blau’s syndrome is the genetic form of what was previously known as early-onset sarcoidosis and is due to mutations of the NACHT domain of the gene CARD15 (or NOD2)." (PMID 24198817, 2013). "The genetic mutation for both has been shown to involve the CARD15/NOD2 gene on chromosome 16q12, inherited in an autosomal dominant pattern in Blau syndrome but arising de novo in infantile sarcoidosis." (PMID 22454749, 2011). "An example of a monogenic autoinflammatory hereditary disease is Blau syndrome: early granulomatous dermatitis with uveitis and arthritis due to an autosomal dominant defect in the NOD2/CARD15 gene on chromosome 16, encoding an intracellular receptor for bacterial peptidoglycans." (PMID 40265442, 2025). "NOD2 variants have been linked to YAOS, Blau syndrome (BS), and Crohn’s disease (CD)." (PMID 38395960, 2024). "In contrast to the understanding that loss-of-function variants of NOD2 were considered nonpathogenic for Blau syndrome, Haploinsufficiency A20 is attributed to loss-of-function variants in TNFAIP3 gene." (PMID 37711606, 2023). "qPCR experiments in both iPS-ML cell lines showed that stimulation with IFNγ for 2 h induced NOD2, regardless of the presence or absence of the Blau syndrome-associated mutation." (PMID 37415984, 2023).
Blau syndrome (continued). "In the iPS-ML cells from 201B7E1, we previously confirmed that NOD2 expression was induced by IFNγ using macrophages induced by further differentiation, similar to observations obtained with iPS-ML cells generated from Blau syndrome patient-derived iPS cells." (PMID 37415984, 2023). "Blau Syndrome (BS) is a rare autosomal dominant noncaseous granulomatous disease caused by mutations in the NOD2 gene." (PMID 37386644, 2023). "Blau syndrome (BS), also known as early-onset sarcoidosis, is a hereditary autosomal dominant disorder resulting from a mutation in the NOD2 (nucleotide-binding oligomerization domain protein 2, or CARD15, caspase recruitment domain family 15) gene." (PMID 37759952, 2023). "These mutations have been found to cause excessive activation of NF-κB and MAPK compared to the wild-type NOD2, leading to the hypothesis that Blau syndrome is the result of gain-of-function NOD2." (PMID 36146565, 2022). "The second case concerned a 16-month-old boy who also carried two variations, a heterozygous nonsense nucleotide substitution mutation in the NOD2 gene, and a homozygous nucleotide deletion mutation in the RFXANK gene, responsible of Blau syndrome and MHC class II deficiency, respectively." (PMID 35529857, 2022). "Therefore, although the molecular mechanisms by which the genetic mutations in NOD2 lead to granuloma formation remain unclear, it is possible that prior exposure to TNFα combined with IFNγ stimulation may provide the impetus for the clinical manifestations of Blau syndrome." (PMID 35711422, 2022). "To determine if NOD2 with a Blau mutation retains the cross-regulatory function of WT NOD2, we first conducted studies of TNBS-colitis in mice with transient over-expression of WT NOD2, Blau syndrome (BS)-NOD2 (bearing the NBD mutation: R314W), and CD-frameshift NOD2 (FS987)." (PMID 36189261, 2022). "A juvenile form of sarcoidosis, Blau syndrome, is caused by NOD2/CARD15 mutations." (PMID 36743677, 2022). "Blau's Syndrome, NFkB activation disorders caused by mutation in NOD2/CARD15 gene, share common clinical features with early-onset sarcoidosis, including recurrent fever, granulomatous dermatitis, sterile arthritis, and ocular inflammation, particularly granulomatours anterior and panuveitis." (PMID 35979409, 2022). "Moreover, At 18 months of age, a genetic analysis revealed heterozygous missense mutation (R334Q) in the NOD2 region of the NOD2/CARD15 gene, He was diagnosed to have Blau syndrome at that point." (PMID 34781959, 2021). "Genetic testing for the NOD2 gene mutation associated with Blau syndrome was not performed due to lack of uveitis, rash, and arthritis seen in this disease." (PMID 34362395, 2021). "Compelling evidence indicates that NOD1 and NOD2 polymorphisms are involved in a great number of immunologic and inflammatory diseases, including Crohn’s disease (CD), Blau syndrome, Behcet’s syndrome, ulcerative colitis (UC), atopic diseases, and early-onset sarcoidosis (EOS)." (PMID 34557182, 2021). "Blau syndrome is a rare but genetically and histologically distinct disease, characterized by a gain-of-function NOD2 mutation and noncaseating epithelioid cell granuloma." (PMID 33923123, 2021). "Moreover, numerous NOD2 mutations in the NBD are associated with IBD, Blau syndrome, and early‐onset sarcoidosis." (PMID 33942347, 2021). "Thus, our data suggest a previously unappreciated T cell defect in Blau syndrome as a consequence of NOD2-dysfunction." (PMID 33106495, 2020). "Here, our work provides evidence for an integral regulatory role for Nod2 in suppression of the TCR-signaling axis in uveitis as might relate to Blau syndrome." (PMID 33106495, 2020). "Moreover, T cells isolated from Blau syndrome patients further underscore how dysregulation of NOD2 results in exacerbated Th17 cells." (PMID 33106495, 2020).
Blau syndrome (continued). "Blau syndrome (BS; OMIM 186580) is a rare dominantly inherited autoinflammatory disorder, associated with mutations in the nucleotide-binding oligomerization domain containing 2 (NOD2) gene." (PMID 31718710, 2019). "Mutations of NOD2 were first described in two rare non-caseating granulomatosis diseases, Blau syndrome and early-onset sarcoidosis, which have been included in the group of NF-κB activation disorders or autoinflammatory granulomatous diseases." (PMID 29881342, 2018). "However, Blau syndrome is a much more homogeneous condition as compared with RA or JIA, especially when the genetic mutation of NOD2 is confirmed." (PMID 24713464, 2014). "Patients who had been diagnosed with Blau syndrome by genetic analysis of NOD2 were recruited." (PMID 24713464, 2014). "Granulomatous autoinflammatory diseases include Blau syndrome (BS, OMIM 186580) and early-onset sarcoidosis (EOS, OMIM 609464); both are caused by mutations in the NOD2/CARD15 gene, with subsequent dysregulation of the inflammatory response and formation of noncaseous granulomas." (PMID 24282415, 2013). "NOD2 gain-of-function mutations leading to uncontrolled NF-κB activation are found in severe autoinflammatory disorders like early-onset sarcoidosis (EOS) and Blau syndrome (BS), underscoring the need to tightly regulate NOD2 activation." (PMID 22829933, 2012). "The third autoinflammatory disorder involving mutations in NOD2, Yao syndrome, has also been described, which is characterized by mutations in the intron of the NOD2 gene, IVS8 + 158, and may be associated with missense mutations in the NOD domain that differ from those in Blau syndrome." (PMID 37415984, 2023). "However, for NOD2 mutations, differential enhancement of NF-κB transcription was dependent on the site of the NOD2 mutation when evaluated in HEK293 cells and the differences did not necessarily correlate with the severity of clinical symptoms in Blau syndrome." (PMID 35711422, 2022). "Interestingly, we identified a paternal heterozygous NOD2 A192 V variant in this patient, but her father had no symptoms of Blau syndrome, and her manifestations were not consistent with Blau syndrome." (PMID 35958611, 2022). "The gene responsible for Blau syndrome (BS)/early-onset sarcoidosis (EOS) is IBD1, and its causative gene product is NOD2." (PMID 34635190, 2021). "Collectively, these observations suggest that sustained surface ICAM-1 expression on and transient PDGF-B production in newly differentiating macrophages that harbor a mutant NOD2 and respond to some stimuli might play a role in granuloma formation in Blau syndrome patients." (PMID 33923123, 2021). "Blau syndrome (BS) and early-onset sarcoidosis (EOS) are rare monogenic autoinflammatory diseases resulting from mutations of the nucleotide-binding oligomerization domain containing 2 (NOD2)/caspase recruitment domain family member 15 (CARD15) gene on chromosome 16." (PMID 34781959, 2021). "Indeed, early studies in HEK cell lines transfected with NOD2 or Blau-variant NOD2 showed excessive NF-κB activity at baseline levels and in response to MDP; thereby implicating over-activation of the canonical Nod2-signaling axis in Blau syndrome." (PMID 33106495, 2020). "Blau syndrome is a triad of synovitis, uveitis and rash with an autosomal dominant inheritance of a mutation in CARD15 (caspase recruitment domain)/NOD2 (nucleotide binding oligomerization domain) on chromosome 16 and may represent a substantial subset of what is called early-onset sarcoidosis." (PMID 22937766, 2012). "Thus, manipulating the levels of NOD2 acylation could be beneficial for treating Blau syndrome." (PMID 37869013, 2023).
Blau syndrome (continued). "Non-inherited NOD2 gene mutations can also cause early-onset sarcoidosis (EOS), a disease similar to Blau syndrome." (PMID 34434197, 2021). "In the granulomatous skin lesion of a Blau syndrome patient, ICAM-1 and PDGF-B were positively immunostained in NOD2-expressing giant cells." (PMID 33923123, 2021). "However, the details as to how NOD2-dysregulation results in Blau syndrome remain unknown." (PMID 33106495, 2020). "Indeed, nucleotide-binding oligomerization domain containing 2 (NOD2) is strongly inducible by IFN-γ in macrophages, and IFN-γ triggers NF-κB activation in macrophages from Blau syndrome patients." (PMID 39868044, 2025). "While genetic mutations in CARD15/NOD2 can be demonstrated in early onset sarcoidosis and Blau syndrome, there has not been a definitive genetic mutation associated with adult sarcoidosis or sarcoidosis in older children, and mutations in CARD15/NOD2 are not found in these patients." (PMID 22937766, 2012).